IL6 (interleukin 6)
Diseases named in the same sentence as IL6 in open-access papers (continued):
Sharing a sentence is not in itself a finding about the gene and the disease.
tumor (continued). "The authors proposed that tumor epithelial cells favor the downregulation of p62 in CAFs leading to reduced mTORC1 activity and c-Myc expression, impaired metabolic detoxification, and release of IL-6 with subsequent promotion of epithelial tumor growth and invasion." (PMID 35582011, 2021). "Moreover, both IL-1β and IL-6 were upregulated in the tumour sample and surgical margin in comparison to the calibrator (RQ > 1)." (PMID 33658555, 2021). "This suggests that IL-6 as a myokine has a tumor-suppressing effect." (PMID 34576053, 2021). "Activation of TLR1/2 heterodimers and TLR2/6 heterodimers in GAMs plays an important role in extracellular matrix remodeling and tumor expansion through induction of matrix metalloproteinases (MMPs), interleukin (IL)-6, and inducible nitric oxide synthase (iNOS)." (PMID 34715891, 2021). "Another cytokine considered a potential tumor maker for CRC is interleukin-6 (IL-6)." (PMID 34071492, 2021). "Besides VEGF, neutrophils are known to secrete other tumor-promoting factors, including hepatocyte growth factor, interleukin-8 (IL-8), IL-6, and tumor necrosis factor, creating a favorable microenvironment for tumor survival." (PMID 33897913, 2021). "The cytokines IL-6 and IL-8 are vital in inflammation and can increase tumor angiogenesis." (PMID 34307378, 2021). "All these data suggest that MSA-induced IL-6 downregulation may impair tumor angiogenesis and then suppressed tumor growth in vivo." (PMID 34393797, 2021). "Therefore, IFN-γ supports the promotion of tumorigenesis by immune evasion, in OSCC-GB patients, through activation of PDL1 transcription in tumor cells via the IL6/JAK/STAT3 signaling pathway." (PMID 33980865, 2021). "Finally, IL-6 has been shown to induce upregulation of the programmed death-ligand 1 (PD-L1) on tumor-infiltrating and circulating myeloid cells." (PMID 34222022, 2021). "Moreover, inhibition of IL-6 production by tumor cells reduces IDO1 expression and tumor-mediated immunosuppressive effects." (PMID 34394118, 2021). "Indeed, IL-6 is a cytokine that promotes angiogenesis, proliferation, and migration of tumor cells and contributes to a favorable environment for metastasis." (PMID 34680345, 2021). "Notably, RA alone was shown to inhibit inflammation in H22 tumor-bearing mice by reducing the IL-1β, IL-6, and TNF-α levels and p65 and p-p65 expression." (PMID 34833849, 2021). "When considering the opposite signaling, we observed an upregulation of Hc cytokine, tumor necrosis factor ligand superfamily member 13b (Tnfsf13b), and the anti-inflammatory cytokine IL-6 only in mice injected with USP7ATRT tumor cells and treated with three systemic injections of ZIKVBR." (PMID 34696533, 2021). "vCAFs promote human intrahepatic cholangiocarcinoma through IL-6/IL-6R crosstalk with tumor cells." (PMID 34858425, 2021). "IL-6, as the main medium of inflammation, is highly expressed in tumor microenvironment." (PMID 34745261, 2021). "However, CAFs are also known to be a potent source of IL-6 in the context of the tumor microenvironment." (PMID 34681685, 2021). "In addition, IL-6 signaling also promotes a tumor hypoxia-resistant/invasive phenotype by triggering NOTCH3-expressing stem/progenitor cells." (PMID 34374886, 2021). "Previous studies showed that IL6 and Tumor necrosis factor α (TNFα) could promote Tregs proliferation in tumor sites." (PMID 34479503, 2021). "Blockade of IL-6 or JAK2 inhibited high-fat-diet-stimulated tumor progression." (PMID 33430277, 2021). "In addition, perioperative pRBC transfusion stimulates tumor growth, the invasion of tumor cells and malignant transformation by increasing the IL-6, vascular endothelial growth factor and hepatocyte growth factor." (PMID 34771598, 2021). "Importantly, the IL6 trans-signaling pathway is involved in most of the harmful effects of IL-6 in chronic inflammatory diseases and in cancer where it leads to switch on IL6-signaling in tumor or stromal cells expressing zero or low level of IL6R." (PMID 34576335, 2021).
tumor (continued). "IL-6 blocked the antitumor immunity reaction in tumor cells." (PMID 34976809, 2021). "However, some other studies found that IL-6 regulates tumor metabolism and inflammatory response disorders by inhibiting the mTOR pathway through the activation of AMPK rather than STAT signals." (PMID 34976805, 2021). "Given the prominent role of IL-6 in microenvironmental signaling and tumor progression, this finding further strengthens the hypothesis that unique TME features of the submandibular gland could affect its prognosis and biological behavior." (PMID 33546179, 2021). "IL-6 is a critical promoter of tumor growth in osteolytic bone metastasis of breast cancer." (PMID 34745140, 2021). "IL-6 secreted by CAFs could promote tumor epithelial–mesenchymal transition in bladder cancer cells." (PMID 33731686, 2021). "Unpolarized or M1 polarized macrophages could be loaded with proinflammatory and M1 polarizing stimuli, such as TNF-α, IFN-γ, or IL-6 to support a proinflammatory environment at the tumor site." (PMID 37849947, 2021). "Notably, the high prevalence of tumors located in the thymi of IL6-/-;Eμ-myc mice was also reflected in a higher number of B cells in the thymi of pre-tumor IL6-/-;Eμ-myc mice compared to IL6+/+;Eμ-myc young mice." (PMID 33651821, 2021). "IL6, a proinflammatory cytokine, has been reported to be influenced by cancer-associated fibroblasts (CAFs) in TME, and participated in the process of human tumor immunity improvement, tumor metastasis and colonization." (PMID 33993869, 2021). "Blocking the interleukin-6 (IL-6) crosstalk between CAFs and epithelial tumor cells negatively affects tumor growth in vitro as IL-6 might mediate the EMT in both subtypes, EAC and ESCC via autocrine and paracrine secretion of this cytokine." (PMID 34572905, 2021). "Treatment of tumor CM from A375SM increased IL-6 mRNA expression level in HMVECs." (PMID 34226586, 2021). "Data from preclinical models showed that inhibition of IL-6 increased the response of PCa to radiation, which was associated with increased oxidative DNA damage, attenuated EMT and MDSC recruitment, and decreased tumor regrowth." (PMID 34109109, 2021). "Additionally, inflammatory cytokines (e.g., transforming growth factor-β and interleukin-6) promote tumorigenesis by enhancing the proliferation, metastasis, and immune escape of tumor cells during chronic inflammation." (PMID 33789590, 2021). "Additionally, tumor-secreted factors, including IL-6 and OSM, activate Signal Transducer and Activator of Transcription 3 (STAT3) within M-MDSCs, which, in turn, drive a mesenchymal and invasive phenotype in the tumor cells." (PMID 34830776, 2021). "Indeed, tumor cell proliferation and migration stimulate inflammatory cytokine production, including IL-6, IL-8, and TNF-α." (PMID 33550763, 2021). "TAMs promote tumor progression by secreting growth factors and different cytokines, including IL-6." (PMID 34638305, 2021). "Indeed, IL-27 is mainly produced by myelomonocytic cells, while IL-6 can be secreted by several other cell types, including T lymphocytes and tumor cells." (PMID 34439164, 2021). "Overall, these findings suggest that IL-6 directly affects MDPs, which in turn, differentiate into metastasis-promoting cells, thereby promoting tumor aggressiveness, an effect which may also exist in humans." (PMID 34140316, 2021). "Increased CAA-released IL-6 and leptin are essential tumour growth enhancers." (PMID 34561446, 2021). "In BC, it may act as a tumor suppressor by recruiting immune effector cells when it is expressed at higher levels in the tumor than in the adjacent healthy tissues, while IL-1β, TNFα, IL-6, and interferon (IFN)γ upregulate CCRL2." (PMID 33670492, 2021). "These may be directly or indirectly tumour-related such as IL-6 which is known to be increased in patients with RCC, although these are only small renal masses." (PMID 34885149, 2021).
tumor (continued). "Surgical resection of the tumour is the only curative treatment for (IL-6 producing) PPGL." (PMID 33715142, 2021). "IL-6 is a pro-inflammatory cytokine released by various cells in the tumor microenvironment, including cancer cells, and thus plays an important role in the expansion and differentiation of tumor cells." (PMID 34764420, 2021). "Moreover, we have studied levels of T lymphocyte tumor infiltration and presence in the tumor periphery in a sub-group of patients selected by high IL-6 serum levels." (PMID 32621022, 2021). "Notably, blocking IL-6 with a neutralizing IL-6 receptor antibody effectively attenuated tumor burden and STAT3 hyperactivation in Apcmin/+Ripk3-/- mice." (PMID 33996591, 2021). "In plasma cell neoplasia, IL-6 is considered as a paracrine proliferation factor that may become an autocrine factor when the tumor proliferation became independent from the cancer micro-environment." (PMID 33708198, 2021). "Especially the expansion of metabolically active MDSCs, as immature granulocyte-differentiation antigen 1-positive (GR-1+) CD11b+ cells secreting large amounts of inflammatory cytokines (mainly TNF-α, IL-1, and IL-6), suggests a late development of the CC in the tumor-bearing host." (PMID 33557173, 2021). "TNBC tumor cells can autonomously produce IL-6, resulting in the constitutive activation of STAT3." (PMID 34067421, 2021). "IL-6 released by CAFs is also known to promote angiogenesis and helps in tumor progression." (PMID 34948209, 2021). "Thus, IL-6 leads to the dysregulation of a plethora of cellular activities that generally promote tumor progression." (PMID 34178680, 2021). "Under tumor conditions, various cytokines, such as GM-CSF, IL6, TNF-α, and other chemokines." (PMID 34479503, 2021). "As a result, IL-6-targeting based therapies have limited benefits for tumor patients." (PMID 34131122, 2021). "Notably, several studies highlighted a key role of tumor cell-produced cytokines, such as IL-6, also in the pro-tumorigenic immunosuppressive network of bone microenvironment." (PMID 34018387, 2021). "Tumor tissue from Il17ra−/− mice presented lower IL6 mRNA expression than that from Il17ra+/− mice." (PMID 33578830, 2021). "IL-17 stimulated the production of IL-6 via tumor cells and tumor-infiltrating immune cells, leading to the activation of the signal transducer and activator of transcription 3 (Stat3) pathway and subsequently tumor growth." (PMID 34332576, 2021). "IL-8, IL-1β, MCP-1, RANTES, TNFα, and IL-6 also promote tumor cell migration and invasion." (PMID 34067089, 2021). "IL6, a multifunctional cytokine, plays an important role in regulating the growth of tumor cells." (PMID 34975504, 2021). "Intriguingly, Chen and colleagues demonstrated that expression of stress-inducible HSP90α on the surface of tumor-cell released autophagosomes (TRAPs) promotes IL-6 production by CD4+ T cells via TLR2-Myeloid differentiation primary response protein 88 (MyD88)- NF-kB signalling pathway." (PMID 34917098, 2021). "Furthermore, in the acidic tumor microenvironment, tumor-activated osteoblasts or mesenchymal stromal cells (MSCs) can secrete inflammatory cytokines, such as IL-6 and IL-8, that, in turn, further boost bone disruption and tumor progression." (PMID 34439218, 2021). "Indeed, within the tumor microenvironment, IL-6 secreted by TNBC cells upregulates CCL5 expression in lymphatic endothelial cells by activating the IL-6 receptor, STAT3, which subsequently enhances transcription of the CCL5 gene." (PMID 34445170, 2021).
tumor (continued). "IL6 was identified originally as a B-cell differentiation factor, but was later found to affect cell growth, activation, and differentiation of multiple immune cells such as B and T lymphocytes, monocytes, dendritic cells, and tumor-infiltrating lymphocytes." (PMID 34411141, 2021). "In the tumor microenvironment, these cells can support dysplastic lesions by promoting angiogenesis and cancer cell proliferation by the release of metalloproteinases (MMPs) and cytokines such as IL-6 and TGF-ß." (PMID 34638361, 2021). "In the analyzed patients, rise of cytokine IL-6 as well as release of tumor marker S100B demonstrated oscillations with a frequency in the range of a few days, suggesting that weekly monitoring of these markers constitutes a minimal requirement in order to identify the expected effects." (PMID 32188047, 2020). "In vitro bioactivity tests showed that HPP has significant immune activity and may alter the tumor microenvironment by regulating the secretion of the inflammatory cytokines NO, IL-6, RANTES, IL-23, and IL-1β." (PMID 32850623, 2020). "In HCC, specifically, EMT has been proven to be crucial in determining tumor progression and metastasis, and can be accelerated by various biological factors, such as inflammatory cytokine interleukin 6 (IL-6), JAK2/STAT3 signaling, and dysregulation of Wnt/β-catenin pathway." (PMID 31949128, 2020). "Alternatively activated M2 macrophages regulate anti-inflammation and reduce NO and reactive oxygen species (ROS) levels but induce Arginase-1, anti-inflammatory cytokines (such as TGF-β, IL-10 and IL-6) and growth factors that support neoplasia and induce tumor cell movement." (PMID 32059469, 2020). "Activin A may also act systemically to induce secretion of IL‐6 from other cell types located distantly from the tumour." (PMID 31436048, 2020). "Tumor microenvironment autophagy in endothelial and stromal cells influences disease progression and response to treatment since it supports tumor progression through the secretion of mitogenic cytokines, such as interleukin-6 (IL6) and interleukin-8 (CXCL8)." (PMID 33604297, 2020). "Tumour hypoxia and necrosis and the subsequent production of lactate result in the local activation of innate immune cells and production of pro-inflammatory cytokines, including interleukin-6 (IL-6), stimulating production of CRP39,40." (PMID 33257741, 2020). "The expression levels of IL-6 and TNFα were reduced in tumor tissues of mice treated with Trichomicin, which was consistent with results of in vitro experiments in which Trichomicin suppressed the expression of IL-6 and TNFα in tumor and stromal cells." (PMID 32317968, 2020). "Furthermore, interaction of cholangiocarcinoma cell-derived EVs with MSCs induces the expression of α-smooth muscle actin, CCL2, CXCL-1, IL-6 in the MSCs which in turn influence the proliferation of tumor cells via enhanced STAT3 phosphorylation." (PMID 32499786, 2020). "We thus hypothesized that skull base patients with high MPV or PDW may have aberrant levels of cytokines such as interleukin-6 and abnormal inflammatory responses, leading to tumour progression and poor outcomes." (PMID 33046024, 2020). "Notably, the NE phenotype can be enhanced by factors in the tumour environment such as cytokines like interleukin-6 (IL6)." (PMID 32802517, 2020). "In conclusion, increased phosphorylation of STAT3 in tumour‐conditioned microglia upregulates the expression of IL‐10 and IL‐6 in an mTOR‐dependent fashion with a concomitant reduction in expression of IL‐12 mediated by reduced phosphorylation and nuclear translocation of NF‐κB." (PMID 32567735, 2020). "Wnt knockdown in M2 monocytes abrogated the increased tumor growth and IL-6 inhibitor resistance—suggesting targeting Wnt signaling may suppress cancer cell induced immunosuppression in melanoma." (PMID 33379189, 2020).
tumor (continued). "Moreover, Hyp-PDT can reduce the cancer cell-secreted tumor-promoting cytokines such as Granulocyte-macrophage colony-stimulating factor (GM-CSF), IL-6, and TNF." (PMID 32340275, 2020). "Also, cytokines that include TNF‐α and IL‐6 are related to the inflammation process and known to typical proinflammatory cytokine with tumor growth effect (Landskron, De la Fuente, Thuwajit, Thuwajit, & Hermoso, 2014)." (PMID 32328255, 2020). "IL-6 stimulation of JAK/STAT3 signaling can occur via an autocrine (cell response to its own secreted signal) or paracrine (signal secreted by other cells in the tumor microenvironment) manner, subsequently contributing to cellular growth and transformation." (PMID 33279931, 2020). "Moreover IL‐6 promotes the polarization of macrophages to a M2 phenotype in the inflamed liver to play pro‐tumor effect." (PMID 32810392, 2020). "In addition, host-IL-6 was shown to be required in the development of cachexia in these mice, with ApcMin/+/IL-6–/– mice showing reduced tumor burden and muscle wasting." (PMID 33329046, 2020). "Our results extend this finding by suggesting that, in some cases, tumor cell-derived IL-6 may act in an autocrine manner to drive the proliferation of residual tumor cells." (PMID 33024122, 2020). "One study reported that serum IL-10 and IL-6 levels correlated with tumor size in HCC patients." (PMID 32443546, 2020). "Moreover, the immune checkpoints B7-H3/CD276 and OX40 were found to be significantly co-expressed with core EMT genes, TGFB1, CXCR4, IL10, and IL6 on tumor microenvironment as vascular endothelial and myeloid cells." (PMID 32708431, 2020). "A parallel serum level increase of interleukin-6 and the tumor marker S100B could be identified in 13 patients, suggesting that the onset of tolerance breakage under checkpoint inhibition may be identified and measured." (PMID 32188047, 2020). "It would suggest that tumor cells and stromal cells interdependently regulate IL-6 expression in cancers, which may account for the localized activation of the IL-6/STAT3 pathway." (PMID 33322216, 2020). "In addition to the selective regulation of cytokine signalling, the activation of STAT3 in tumor cells was disturbed, and the increase in proinflammatory cytokines such as IL-6 was further prevented." (PMID 33082817, 2020). "MDSCs play an immunosuppressive role in the tumor microenvironment as it produces IL-6 and NO." (PMID 32723346, 2020). "Expression of the tumor-promoting inflammatory factor IL-6, immunosuppressive factor PD1, and PD-L1 increased, whereas expression of the immune factor TNF-α and body rhythm-related factors Per1 and Per2 decreased in the night-shift group, and the difference was statistically significant." (PMID 33083827, 2020). "In particular, serum IL-6 has been identified as elevated across a number of tumor types and is associated with a negative prognostic effect and higher tumor stage." (PMID 33622996, 2020). "Likewise, curcumin reduced the frequency of MDSCs in the tumor and the spleen of tumor-bearing mice that was correlated to the reduction of IL-6 which is known to influence the function of MDSCs." (PMID 32849585, 2020). "Notably, an increased level of the tumor suppressor, miR-142-3p, whose targets include LGR5, IL-6, and ABCG2, was detected in association with MSI-N1014 treatment." (PMID 32560222, 2020). "IL-6, commonly secreted by macrophages, DCs, MDSCs, and tumor cells, is a pleiotropic proinflammatory cytokine that is involved in almost all aspects of the immune system, from the infiltration of neutrophils at the site of infection to the generation of T cell responses." (PMID 32561709, 2020). "Hence, simultaneously inhibiting IL-6 and IL-8 expression was a more lucrative line of action to induce appreciable changes in tumor growth." (PMID 32211043, 2020). "Immunomodulatory CAFs expressing highly IL-6/CXCL12 identified could activate JAK/STAT signaling in tumor cells, just like iCAFs." (PMID 33292666, 2020).